NUMBL (NUMB like endocytic adaptor protein)
Diseases named in the same sentence as NUMBL in open-access papers (continued):
Sharing a sentence is not in itself a finding about the gene and the disease.
tumor (continued). "Breast and lung tumor databases also exhibited a variable number of tumor samples with downregulated NumbL mRNA levels, which does not account for a significant decrease of the total tumor population (data not shown)." (PMID 27613838, 2016). "Furthermore, an absence of NumbL induces chemoresistance in tumor cells." (PMID 27613838, 2016).
cancer (8 papers, 2015 to 2023). A tumor composed of atypical neoplastic, often pleomorphic cells that invade other tissues. "Five hypermethylated regions were in genes previously associated with cancer (TRAP1, SLC38A3, CHRM1, EDN2, and PROX1), while six hypomethylated regions were in genes previously associated with cancer (NUMBL, ALDH1B1, FTCD, FASTKD2, FAM96A, and ARHGAP15)." (PMID 36474183, 2022). "However, it remains absent that a systematic assessment of the mechanisms underlying NUMB and its homologous protein NUMBLIKE (NUMBL) involvement in cancer." (PMID 37657045, 2023). "NumbL, a closely related homologue to Numb, has been recently linked to cancer." (PMID 27613838, 2016). "Compared to NUMB, less is known about the expression and role of NUMBL in most types of cancer until now." (PMID 37657045, 2023). "To date, the ultimate mechanisms of NUMB and NUMBL mediating cancer processes concentrate on breast, lung, colon, prostate, liver, and pancreatic cancers." (PMID 37657045, 2023). "Emerging publications have reported functional links between NUMB/NUMBL and clinicopathologic features in many types of cancers." (PMID 37657045, 2023). "It is differential that the expression status of NUMB and NUMBL across various cancer types of TCGA." (PMID 37657045, 2023). "In short, the observations above illustrated that relative mRNA expressions of NUMB/NUMBL were significantly related to patients individual cancer pathological stages." (PMID 37657045, 2023). "Herein, the corresponding heatmap also showed a positive correlation between NUMB or NUMBL and their above targeting genes in the majority of detailed cancers." (PMID 37657045, 2023). "This phenomenon suggests that NUMB and NUMBL act as essential regulators of cancer cell properties, individually acting in a dose-dependent manner and regulating the same pathway with a certain degree of redundancy." (PMID 29507685, 2018). "Inhibition of only one NUMB family protein is sufficient to modify cancer cell properties, since a partial decrease in NUMB or NUMBL is sufficient to increase Notch pathway activation and cancer stem-like properties." (PMID 29507685, 2018). "Next, we tested the ability of cells with reduced levels of NumbL to form tumorspheres, another surrogated assay for the cancer stem-like phenotype." (PMID 27613838, 2016). "The results indicated that resistant cells have an increased proportion of CD44+/CD24− cells being enriched in cancer stem-like cells, mainly when NumbL is downregulated." (PMID 27613838, 2016). "This study aimed to investigate the prognostic significance for NUMB and NUMBL in pan-cancer." (PMID 37657045, 2023). "Consequently, these results furnish novel expectations into the functional roles of NUMB/NUMBL in diversified human malignancies, emphasizing the potential molecular mechanisms of NUMB/NUMBL in the tumorigenicity and clinical prognosis in different cancers." (PMID 37657045, 2023). "Finally, we utilized a flow chart to show the screening procedure of NUMB/NUMBL in pan-cancer more scrupulously." (PMID 37657045, 2023). "Therefore, cells with lower NUMBL levels are more resistant to drugs that are commonly used in cancer chemotherapy, such as doxorubicin or vincristine." (PMID 29507685, 2018). "Thus, it is plausible that the NUMB and NUMBL isoforms are essential in terms of their different regulatory effects on the properties of cancer." (PMID 29507685, 2018). "Furthermore, a partial decrease in NumbL is sufficient to increase Notch pathway activation and the cancer stem-like properties." (PMID 27613838, 2016). "Furthermore, epigenetics mutation frequency of NUMBL is higher than NUMB among different cancers, and altered NUMBL, rather than NUMB, associated to lower OS and DFS of UCEC patients." (PMID 37657045, 2023). "Therefore, there are contradictory data about the role of NumbL in cancer progression." (PMID 27613838, 2016).
cancer (continued). "Deregulation expression of NUMBL and RORC have been reported to be involved in the regulation of cancer cell migration, invasion, and metastasis." (PMID 37373553, 2023). "Although the roles of NUMB/NUMBL in the tumorigenesis and prognosis of several cancers have been partially confirmed, further systematical analysis, especially pan-cancer analysis, of NUMB/NUMBL has yet to be elucidated." (PMID 37657045, 2023). "Our aim in this study was to investigate the role of NumbL in tumorigenesis, specifically the control of the CSC phenotype, which has emerged as a preferred target in cancer therapy because of its role in cancer recurrence." (PMID 27613838, 2016). "This study highlights the predictive roles of NUMB and NUMBL in pan-cancer, suggesting NUMB and NUMBL might be served as potential biomarkers for diagnosis and prognosis in various malignant tumors." (PMID 37657045, 2023). "In accordance with our results, a pan-cancer analysis systematically investigates the role and function and relevant molecular mechanisms of NUMB and NUMBL in majority types of cancer, and discusses the similarities and divergences between these 2 homologous proteins." (PMID 37657045, 2023). "Importantly, the downregulation of NUMBL also triggers Notch pathway activation, further increasing the epithelia-mesenchymal transition (EMT), cancer stem cell (CSC) transcriptional markers and CSC-like phenotypes." (PMID 29507685, 2018). "Furthermore, NumbL downregulation increases epithelial-mesenchymal transition (EMT) and cancer stem cell (CSC)-related gene transcripts and CSC-like phenotypes, including an increase in the CSC-like pool." (PMID 27613838, 2016).
NUMBL also shares sentences with these, for which no sentence is quoted: breast carcinoma (2 papers); glioblastoma (2); adrenocortical carcinoma (1); aortic stenosis (1); bladder cancer (1); cervical squamous cell carcinoma (1); colon adenocarcinoma (1); endocervical adenocarcinoma (1); pheochromocytoma (1); prostate carcinoma (1); testicular germ cell tumor (1); uveal melanoma (1); viral infection (1).